ITGA11 (integrin subunit alpha 11)
Diseases named in the same sentence as ITGA11 in open-access papers (continued):
Sharing a sentence is not in itself a finding about the gene and the disease.
skin tumor (2 papers, 2019 to 2022). "To evaluate the relevance of integrin α11β1 integrin signaling in skin carcinogenesis, we compared the development and progression of DMBA/TPA-induced skin tumors between α11-deficient (Itga11−/−) and control mice (Itga11+/+) mice." (PMID 36003785, 2022). "Similar to our observations in Itga11−/− skin tumors, LOXL1 expression was decreased in Itga11−/− mouse embryonic fibroblasts." (PMID 36003785, 2022). "A marked reduction in the number of skin tumors was apparent already at week 10, and at weeks 20–28, the Itga11−/− mice had, on average, 50% fewer papillomas than the Itga11+/+ mice." (PMID 36003785, 2022). "Hyperplastic skin can be considered to represent an early step in skin tumor development and was induced in Itga11−/− and Itga11+/+ mice by repeated treatments of TPA." (PMID 36003785, 2022). "TGFβ1 induces α11 expression in skin myofibroblasts during wound healing, and we observed higher levels of TGFβ1 in Itga11-/- skin tumors as compared to Itga11+/+ tumors." (PMID 36003785, 2022). "Nevertheless, our findings on reduced PDGFRβ expression in the absence of α11, not only in Itga11-/- skin tumor stroma but also in chronically inflamed dermis, suggest the need for further studies on integrated α11β1 and PDGFRβ signaling." (PMID 36003785, 2022). "Hence, we analyzed the expression of selected ECM components in skin tumors by qRT-PCR and found that the mRNA levels of α1 chains of collagen I (Col1a1) and III (Col3a1) and Tnc were significantly higher in Itga11+/+ papillomas than in Itga11−/− papillomas." (PMID 36003785, 2022). "However, according to our data, the Itga11-/- skin tumor CAFs do not respond as efficiently to TGFβ1 induction as the control CAFs, as demonstrated by the downregulation of fibrillar collagen and TNC biosynthesis in the knockout tumors." (PMID 36003785, 2022). "Considering these data regarding PDAC, our observations regarding the defects in the activation of matrix-producing CAFs, LOX upregulation, and the formation of dense and aligned collagen matrix and the impaired growth of skin tumors in Itga11-/- mice are not necessarily contradictory." (PMID 36003785, 2022).
Acidosis (1 paper, 2022). Abnormal acid accumulation or depletion of base. "Additionally, the top seven nodes of the “Acidosis” network were present among the top ten nodes of “Acidosis and Bone metastasis”: COL1A1, COL3A1, COL4A1, COL4A2, ITGB3, THBS2, and ITGA11." (PMID 35159353, 2022).
allergic asthma (1 paper, 2022). A asthma with a basis in a pathological type I hypersensitivity reaction. "First, the detailed mechanism by which lncRNA ENST00000499459 interacted with DXIDC1/ITGA11 in allergic asthma was not investigated, which requires further functional experiments." (PMID 36463267, 2022).
Alzheimer disease (1 paper, 2021). A progressive, neurodegenerative disease characterized by loss of function and death of nerve cells in several areas of the brain leading to loss of cognitive function such as memory and language. "Ten DEGs, including IGF1, VEGFC, RAPGEF3, PIK3CA, Akt3, ITGB3, ITGA11, SPP1, NOS1, and ATP6V0B, were selected from Rap1, oxidative phosphorylation, and Alzheimer’s disease signaling pathways." (PMID 34359260, 2021).
aneurysm (1 paper, 2025). Bulging or ballooning in an area of an artery secondary to arterial wall weakening. "In contrast to other widely studied integrin members, ITGA11 has been rarely reported in studies related to aneurysm formation." (PMID 40275351, 2025).
asthma (1 paper, 2022). "We speculate that the increased expression of ITGA11 in PBMCs would indicate the inflammatory state of asthma exacerbation to some extent." (PMID 36463267, 2022).
cholangiocarcinoma (1 paper, 2018). A carcinoma that arises from the intrahepatic biliary tree (intrahepatic cholangiocarcinoma) or from the junction, or adjacent to the junction, of the right and left hepatic ducts (hilar cholangiocarcinoma). "For example, cholangiocarcinoma (CHOL) overexpresses a large variety of subunits (e.g. ITGAV, ITGA1, ITGA4, ITGA5, ITGA11, ITGB1, ITGB2, ITGB6), whereas, the equally deadly pancreatic adenocarcinoma (PAAD) overexpresses a very limited set of integrins, including ITGA6 and ITGB4." (PMID 30046394, 2018).
Cirrhosis (1 paper, 2024). A chronic disorder of the liver in which liver tissue becomes scarred and is partially replaced by regenerative nodules and fibrotic tissue resulting in loss of liver function. "Comprehensive transcriptome assay demonstrated that miR-12135 suppressed Integrin Subunit Alpha 11 (ITGA11) and that ITGA11 expression is correlated with alpha smooth muscle actin expression in patients with cirrhosis." (PMID 38235326, 2024).
Cognitive impairment (1 paper, 2023). Abnormal cognition is characterized by deficits in thinking, reasoning, or remembering. "Among the three inflammatory/immune proteins negatively correlated with EDII scores, one protein (ITGA11) was significantly associated with decreased odds of incident cognitive impairment in the same covariate-adjusted model." (PMID 36737481, 2023). "Results provide insights into how inflammatory nutritional patterns are associated with an immune-related proteome and identify a group of proteins (CXCL10, CCL3, HGF, OPG, CDCP1, NFATC3, ITGA11) related to future cognitive impairment over a 14-year follow-up period." (PMID 36737481, 2023). "In addition to demonstrating their relationship to inflammatory diet and incident cognitive impairment/dementia, we identified OPG, HGF, NFATC3, CDCP1, and ITGA11 as differentially expressed at the RNA level in brain tissue of deceased individuals with pathologically defined AD." (PMID 36737481, 2023).
craniosynostosis (1 paper, 2011). Craniosynostosis is defined as the premature fusion of one or more cranial sutures leading to secondary distortion of skull shape resulting in skull deformities with a variable presentation. "Most interesting is the fact that one study observed general downregulation of alpha integrin subunits (ITGAs) in syndromic craniosynostosis, except for ITGA11; exactly what was observed in this study." (PMID 22028906, 2011).
E. coli infection (1 paper, 2016). "We identified only two lncRNAs in U251 cells, lnc-ITGA11-1 and lnc-DIRC1-1, for which the levels were not affected by meningitic E. coli infection, while the remaining ones exhibited similar decreases in hBMECs, U251 cells and HUVECs." (PMID 27958323, 2016).
follicular thyroid carcinoma (1 paper, 2019). "Although ITGA2 has been shown to be a target gene for certain microRNAs in aggressive papillary thyroid carcinoma, the impact and significance of its increased expression in follicular thyroid carcinoma cells upon PROX1 silencing, like that of the ITGA11 downregulation, remains to be clarified." (PMID 31060342, 2019).
glioma (1 paper, 2023). A benign or malignant brain and spinal cord tumor that arises from glial cells (astrocytes, oligodendrocytes, ependymal cells). "In addition to the induction of ITGB3, we observed that TWEAK treatment also elevated the expression of ITGA11, which has previously been described in glioma invasion." (PMID 36945490, 2023).
keloid (1 paper, 2025). An irregularly shaped, elevated mark on the skin caused by deposits of excessive amounts of collagen during wound healing. "Additionally, other keloid-associated genes, especially those with functions related to extracellular matrix like ITGA11, are necessary for bone formation, repair, and maintenance." (PMID 40835838, 2025).
Lassa fever (1 paper, 2021). A viral hemorrhagic fever that is caused by the Lassa virus, which is transmitted by contact with infected rodents; it is characterized by fever, headache, malaise, myalgia, and hearing loss. "Genes involved in extracellular matrix and cell-adhesion were also modulated, particularly during fatal Lassa fever (NID1, TIMP3, ITGA11, TGM2, MMP8/9, OLFM4, PCDH20, and CADM3), as well as some others involved in coagulation (SERPIN, TFPI2) and apoptosis (CLU, BCL2L14)." (PMID 33398113, 2021).
liver diseases (1 paper, 2023). "Disease annotations suggested three of the proteins are linked to different types of cancer (CDCP1, CCL3, ITGA11), whereas another two are related to liver diseases (CXCL10, HGF)." (PMID 36737481, 2023).
liver fibrosis (1 paper, 2024). "In summary, miR-12135 that was upregulated by equol suppressed liver fibrosis and downregulated ITGA11 which was increased in activated hepatic stellate cells." (PMID 38235326, 2024). "In conclusion, knockdown of miR-12135 target ITGA11 significantly suppressed CDAHFD-induced liver fibrosis in this mouse model." (PMID 38235326, 2024). "Our results showed that ITGA11 knockdown strongly suppressed liver fibrosis in the CDAHFD model." (PMID 38235326, 2024). "miR-12135 suppressed the expression level of ITGA11 and liver fibrosis." (PMID 38235326, 2024). "Thus, miR-12135/ITGA11 could be a novel target in the suppression of liver fibrosis." (PMID 38235326, 2024). "Consistent with CDAHFD-induced liver fibrosis, miR-12135 attenuated BDL-induced ITGA11 and P-SMAD2/3 increases." (PMID 38235326, 2024). "Considering the significant correlation between the expressions of ITGA11 and ASMA (the major severity marker for liver fibrosis), a positive feedback loop may contribute to the excess activation of hepatic stellate cells." (PMID 38235326, 2024).
malnutrition (1 paper, 2019). Inadequate nutrition resulting from poor diet, malabsorption, or abnormal nutrient distribution. "Itga11 deficient mice are growth retarded and have smaller bones, but this was thought to reflect a defect in incisor development that leads to malnutrition." (PMID 30632962, 2019).
Obesity (1 paper, 2024). Accumulation of substantial excess body fat. "For example, ITGA11 on chromosome 1 is associated with an obesity index that determines fat deposition in pigs and other animals." (PMID 38254405, 2024).
papilloma (1 paper, 2022). A benign epithelial neoplasm that projects above the surrounding epithelial surface and consists of villous or arborescent outgrowths of fibrovascular stroma. "When the red and green signals were quantified, the ratio of thick/thin collagen fibers was approximately twofold higher in the Itga11−/− papillomas as compared with that in the Itga11+/+ papillomas." (PMID 36003785, 2022). "The FACS analysis showed that the Itga11−/− papillomas harbored significantly more macrophages and CD8+ T-cells and significantly fewer CD4+ T-cells and neutrophils than the Itga11+/+ papillomas." (PMID 36003785, 2022). "The immunofluorescence staining of mouse tumor tissues revealed prominent LOX signals in Itga11−/− papillomas, whereas there were clearly fewer in Itga11+/+ papillomas." (PMID 36003785, 2022). "We found that the mRNA levels of αSMA and PDGFRβ, markers of activated myofibroblasts and CAFs, were significantly lower in the Itga11−/− papillomas as compared with the Itga11+/+ papillomas." (PMID 36003785, 2022). "The mRNA levels of prolyl 4-hydoxylases-1 (Pdha1) and -2 (Pdha2), the key enzymes in collagen biosynthesis, were also significantly downregulated in Itga11−/− papillomas." (PMID 36003785, 2022). "However, the quantification of signal intensities did not reveal significant differences in PDGFRβ or αSMA expression between the Itga11−/− and Itga11+/+ papillomas." (PMID 36003785, 2022). "Hence, our data indicating significantly higher levels of TGFβ1 in Itga11-/- papillomas than in Itga11+/+ papillomas suggest that enhanced TGFβ1 signaling could be one reason for the reduced tumor cell proliferation and impaired primary tumor growth." (PMID 36003785, 2022).
prostate carcinoma (1 paper, 2022). A carcinoma that arises from epithelial cells of the prostate gland. "To address and confirm the associations of SRD5A2 and ITGA11 protein levels with clinicopathological features, we used IHC assay on a prostate cancer tissue array, which contains tumor tissues from 42 patients." (PMID 35293897, 2022).
renal fibrosis (1 paper, 2022). A final common manifestation of a wide variety of chronic kidney diseases characterized by glomerulosclerosis and tubulointerstitial fibrosis. "Based on previous studies, we determined that injury caused by crystal deposition is frequently accompanied by renal fibrosis and that THBS1, ITGA11, and SOCS2 can affect the fibrotic process." (PMID 34997271, 2022).
small cell lung carcinoma (1 paper, 2025). Small cell lung cancer (SCLC) is a highly aggressive malignant neoplasm, accounting for 10-15% of lung cancer cases, characterized byrapid growth, and early metastasis.
stomach adenocarcinoma (1 paper, 2021). "Moreover, ITGA11 was chosen to validate its oncogenic role in stomach adenocarcinoma (STAD)." (PMID 34222028, 2021). "Furthermore, dysregulated prognosis-related ITGs were systematically identified in each cancer type, including ITGA11 in stomach adenocarcinoma (STAD)." (PMID 34222028, 2021).
Stroke (1 paper, 2023). Sudden impairment of blood flow to a part of the brain due to occlusion or rupture of an artery to the brain. "The biomarkers CLEC4G, CKAP4, IL6, LY75 and ITGA11 were found to be significantly associated with stroke severity as measured by mRS and in case of IL6 and ITGA11 also by NIHSS." (PMID 37468969, 2023). "The present study confirmed the positive associations between stroke severity and IL6 and CKAP4, but also elucidated novel associations, namely between CLEC4G, LY75 and ITGA11, which enrich the present knowledge of blood biomarkers associated with stroke." (PMID 37468969, 2023). "LY75 and ITGA11 were associated with lower stroke severity and might serve as potential therapeutic targets for promoting tissue repair and recovery following stroke." (PMID 37468969, 2023). "Higher relative concentrations of plasma CLEC4G, CKAP4, and IL-6 were associated with higher stroke severity, whereas LY75 and ITGA11 showed an inverse association." (PMID 37468969, 2023). "At last, ITGA11 showed a negative association with stroke severity as measured by mRS and NIHSS." (PMID 37468969, 2023). "Therefore, ITGA11 may indeed have a protective role in stroke pathophysiology and may serve as a potential therapeutic target for promoting tissue repair and recovery following stroke." (PMID 37468969, 2023).
systemic sclerosis (1 paper, 2022). A chronic disorder, possibly autoimmune, marked by excessive production of collagen which results in hardening and thickening of body tissues. "In fact, an early study showed that PDGFRβ is highly expressed in fibroblasts in skin biopsies of systemic sclerosis (SS) patients, and a recent scRNA-seq analysis identified ITGA11 as enriched in SS skin myofibroblasts." (PMID 36003785, 2022).
triple-negative breast carcinoma (1 paper, 2024). An invasive breast carcinoma which is negative for expression of estrogen receptor (ER), progesterone receptor (PR), and human epidermal growth factor receptor 2 (HER2). "In addition to the previous report that integrin α6β1-activated FAK induces GLI-1 expression in triple-negative breast cancer, our present results with ITGA11 KD demonstrated that integrin α11 induced activation (nuclear translocation) of GLI-1, but not HIF1α and EZH2." (PMID 38664825, 2024).
viral infection (1 paper, 2014). "Among all the regulated genes, only one cytoskeleton-related gene (integrin, alpha 11, ITGA11) was up-regulated at 24 h post-viral infection." (PMID 25344771, 2014).
tumor (40 papers, 2012 to 2025). "In this scenario and according to our findings, α11 integrin (ITGA11) is significantly overexpressed in the breast stromal compartment and linked to aggressive tumor features, such as high histologic grade and proliferative rate." (PMID 38937754, 2024). "In the preclinical MMTV-PyMT mouse model, ITGA11 deficiency led to a drastic reduction of tumor progression and metastasis." (PMID 39335478, 2024). "Elevated ITGA11 levels were associated with higher tumor grade (G1 vs. G2 and G3, 20.0% vs. 34.9% and 42.1%, respectively, p = 0.044)." (PMID 29383106, 2017). "ITGA11 specifically has been identified as a key player in tumor dynamics, as it is expressed by cancer-associated fibroblasts within the tumor microenvironment; is associated with aggressive tumor phenotypes; and is known to be upregulated in different kinds of cancerous or fibrotic lesions." (PMID 40835838, 2025). "Firstly, the ITGA11 profile in GC tissues and paracancerous non-tumor tissues was assessed by quantitative reverse transcription-polymerase chain reaction (qRT-PCR) and Western blot (WB), and the association between ITGA11 and GC patients’ clinicopathological indicators was evaluated." (PMID 34802381, 2021). "Nonetheless, intra-tumoral Itga11+ cells were readily detectable at both the tumor periphery and within the tumor core, indicating their insensitivity to androgen deprivation." (PMID 41327318, 2025). "This is consistent with reports that ITGA11 expression in CAF is required for CAF-induced tumor cell invasion and that CAF deposit ECM tracks enriched with the YAP1 target gene and C3 marker ITGB5, which serve as guidance cues for cancer cell migration." (PMID 41327318, 2025). "ITGA11 promotes CAF invasion and CAF-induced tumor cell invasion, and associates with high-grade tumors and poor prognosis." (PMID 40766310, 2025). "Given the marked difference in tumor growth between the Itga11+/+ and Itga11−/− mice, we addressed the impact of α11 in tumor cell proliferation by determining the numbers of actively dividing cells in tumor tissue sections." (PMID 36003785, 2022). "Impaired tumorigenesis in the Itga11−/− mice was seen even more clearly when the tumor multiplicity between these and the Itga11+/+ controls was compared." (PMID 36003785, 2022). "Masson trichrome staining did not reveal obvious differences in the collagen content of tumors, although areas with hyalinized collagen, suggestive of thicker collagen fibers, were frequently observed in the Itga11−/− tumor stroma." (PMID 36003785, 2022). "Upregulated genes included cartilage-associated genes (COMP, MATN3, and COL11A2), collagen- and extracellular matrix-associated genes (COL9A2, SFRP2, and SERPINE2), and tumor metastasis- and progression-associated genes (SLC38A3, FST, ITGA11, and DGKI)." (PMID 36192442, 2022). "The rough endoplasmic reticulum (rER) was prominent and highly dilated in the Itga11+/+ tumor fibroblasts, whereas it was clearly less dilated in the Itga11−/− CAFs." (PMID 36003785, 2022). "Our data suggesting lower fibrillar collagen biosynthesis on the part of α11-deficient CAFs are congruent with the less active rER in these cells but stand in contrast with the observed well-organized collagen bundles in the Itga11−/− tumor stroma." (PMID 36003785, 2022). "The recent analysis of ITGA11, using highly selective mAbs, demonstrated expression of α11 in subsets of CAFs in various tumor types." (PMID 33682233, 2021). "Together with our data on miR-204 affecting fibroblast cell motility, this suggests that the tumor suppressive effect of miR-204 is mediated via ITGA11." (PMID 34769388, 2021). "These conclusions corroborated that attenuating ITGA11 exerted anti-tumor effects by restraining PI3K/AKT in GC cells." (PMID 34802381, 2021). "The tumor-suppressive effect mediated by ITGA11 knockdown was attenuated after activating the PI3K/AKT pathway with insulin-like growth factor 1 (IGF-1)." (PMID 34802381, 2021).